IFNG (interferon gamma)
Diseases named in the same sentence as IFNG in open-access papers (continued):
Sharing a sentence is not in itself a finding about the gene and the disease.
infection (continued). "In the early stage of infection, this immune response is modulated towards a Th1-mediated immune mechanism by interferon-gamma (IFN-γ), but when an infection establishes itself in the host, the overall response gradually develops towards a Th1/Th2 balance." (PMID 37887717, 2023). "Currently, our understanding of which cells produce IFNγ and where they are located at different stages of an infection is limited." (PMID 37842651, 2023). "In the context of Tc infection, increased gene expression of innate immune responses and IFNγ and IL10 cytokines was noted in human placental explants exposed to Tc50." (PMID 38104118, 2023). "Those with either High IgG and Low IFNγ responses or Low IgG and High IFNγ responses had an intermediate risk of breakthrough; however, it cannot be concluded from this analysis whether high IgG or high IFNγ responses are individually associated with a lower rate of vaccine breakthrough infection." (PMID 37655880, 2023). "We explored this further by studying the ANKRD13A-associated proteins p97/VCP and UBXD1 at the PV and show that they act in defense against Tg infection in IFNγ-stimulated human cells." (PMID 37975677, 2023). "To this end, we employed MS to identify ANKRD13A as a novel ubiquitinated protein during Tg infection in IFNγ-stimulated epithelial cells." (PMID 37975677, 2023). "Conversely, infection significantly reduced levels of IL-1α, IL-2, IL-9, IL-10, IL-12 (p70), IL-13, IFNγ, IL-3, CCL4 (MIP-1β), CSF 2 (GM-CSF), CCL5 (RANTES), and TNFα." (PMID 37790429, 2023). "As THP-1 cells have been reported to undergo cell death upon IFNγ-induction and infection with Tg, we analyzed the infection readouts of percent replication and vacuole size at 18 h p.i.; parameters that do not depend upon total cell number." (PMID 37975677, 2023). "Predisposition to infection is mediated by gene mutations encoding IFNγR1, STAT1, STAT3, CD40L, or GATA2 (responsible for type 1 immune response), IFNγ neutralizing autoantibodies." (PMID 38143753, 2023). "In our experiment, after infection, the parasitic burden on classically activated macrophages was reduced by half, and the upregulation of genes involved in the innate and interferon gamma responses was observed." (PMID 37235312, 2023). "The analysis of precursor populations revealed an overall similar tendency between WT and IFNγ-/- mice upon infection, with an increase of all populations in infected mice compared with uninfected mice." (PMID 37383236, 2023). "While IL-6 is predominantly associated with disease severity in TB, knockout studies have shown that IL-6 plays an important role in controlling bacterial load early in the infection through induction of protective interferon gamma-producing T cell responses." (PMID 37653422, 2023). "Together these data suggest that IFNγ is partly dispensable for the occurrence of EM upon the infection of mice with M. tuberculosis HN878, consequently suggesting the occurrence of alternative mechanisms." (PMID 37383236, 2023). "The paramount immune factor against T. gondii is interferon-gamma (IFN-γ), which orchestrates effector mechanisms that will successfully kill the parasite during the acute phase of the infection, as well as keep the latent stages quiescent (9, –, 12)." (PMID 37768053, 2023). "Prior work on BNZ treatment showed improvement of infection-induced immunological perturbations 76, but with incomplete IFNγ restoration." (PMID 36711878, 2023). "Pre-treatment of both sgAAVS1 and sgSPOP cells with IFNγ reduced vesicular stomatitis virus (VSV) progeny virus production by approximately fivefold in a multi-cycle infection experiment." (PMID 37622993, 2023). "Toxoplasma gondii elicits a typical Type II IFNγ‐mediated host immune response to resolve infection and clear parasites." (PMID 37259639, 2023). "We also provide evidence that NKT cells, ILC1s, and γδ T cells also produce Ifnγ early during infection as other studies have described." (PMID 37842651, 2023).
infection (continued). "In the acute infection, the robust Th1 immune response, characterized by production of proinflammatory cytokines, as interferon-gamma (IFNγ) and tumor necrosis factor (TNF) is required for an efficient antiparasitic response." (PMID 35572567, 2022). "Reports further show an increase of some cytokines, including TNF-α, interferon-gamma (IFN-γ) and IL-6, over time during infection." (PMID 36184636, 2022). "BALB/c mice were infected with 105 TCID50 maVie16 and treated intraperitoneally on days 1 and 3 post infection (p.i.)with a mix of 500 μg anti-IFNγ and anti-TNF or with isotype control antibody." (PMID 35023830, 2022). "The diagnosis of the infection is carried out through the direct test, culture, histopathology, tuberculin skin test, polymerase chain reaction, interferon-gamma release assay, and genotyping." (PMID 34996655, 2022). "In situ studies revealed a profuse recruitment of myeloid cells and of IFNγ- and IL-4-producing T lymphocytes to the site of infection, and the typical histopathological changes induced by dermotropic Leishmania species." (PMID 35770175, 2022). "Infection of vaccinated mice with PbA increased the number of IFNγ-producing CD8T cells (Vac PbA: 1.4%, 88 × 103 cells, mean value) to a lesser extent than the infection of unvaccinated control mice (approximately 50% less)." (PMID 35632518, 2022). "It has been shown that the secretion of IFNγ by lymphocytes correlates with the degree of protection of animals immunized with low-virulent isolates from infection by a homologous virulent strain." (PMID 36032295, 2022). "Immune interferon-gamma (IFN-γ) plays an important role in fighting infection and exerts its effects through an extensive transcriptional program involving approximately 2000 genes, of which the Guanylate-binding proteins (GBP) family is an important member." (PMID 36405762, 2022). "Infection with HSV-1 resulted in the generation of predominately IFNγ producing Th1 cells, and assessment of the divided cells (CFSElo) revealed that 78% downregulated CD62L, 5% upregulated CCR6, while 70% upregulated CXCR3." (PMID 35637249, 2022). "For example, interferon-gamma (IFN-γ) protein was detected on day 5 post infection in adult animals but day 7 post infection in aged animals." (PMID 35650631, 2022). "In these mice, there is an early and unsustained increase in pulmonary bacterial burden and decrease in IFNγ and TNFα after low dose aerosol infection with virulent Mtb strain H37Rv." (PMID 35371092, 2022). "While IL6 levels were lower in SARS-CoV-2+ children as compared to adult patients, the expression of other pro-inflammatory cytokines such as IFNγ and TNFα directly correlated with early age infection and symptoms." (PMID 35626859, 2022). "Consistently, infection with KP36WT triggered significantly higher IFNγ responses compared to infection with KP36WT(25c > t)." (PMID 36095213, 2022). "In the E10.5 infection group, only transcripts for Ifnγ were elevated, while all other targets remained unchanged." (PMID 35312688, 2022). "Upon infection, M. bovis mycobacteria initially interact with resident macrophages in the lung tissues which, in turn, become activated and act to control the infection via Th1-type cytokines, mainly IFNγ." (PMID 35889984, 2022). "On Day 0, M(IFNγ/LPS) displayed significantly enhanced mycobacterial killing at 27- and 51 hr post infection, whereas M(4/13) displayed comparable killing capacity to naive M(-)." (PMID 36173104, 2022). "A previous mammalian study reports that interferon-gamma (IFN-γ) has potential anti-bacterial bioactivity against infection in vitro; however, its capacity in vivo is ambiguous." (PMID 35812858, 2022). "CD8+ T cells are essential for adaptive immune responses against infection as they secrete cytokines such as interferon-gamma (IFN-γ) and tumor necrosis factor-alpha (TNF-α)." (PMID 36362727, 2022).
infection (continued). "Instead, in these animal models T-cells and in particular IFNγ and TNFα responses are critical for controlling early infection and mediating bacterial clearance." (PMID 35812430, 2022). "IFNγ was detected as early as week 2 of infection in Mtb-HT1 infected mice but remained undetectable up to 3 weeks in Mtb-LT1 infected mice, and then rising to levels equivalent to Mtb-HT1 at 4 weeks." (PMID 35173157, 2022). "Guanylate binding protein 1 (GBP1) and guanylate binding protein 5 (GBP5) are two member of the GBP family and mediate cellular response to IFNγ in infection and inflammation." (PMID 35187081, 2022). "Even though Th1 cells through IFNγ and TNFα are required for host control of mycobacteria, their enhanced activity in anti-PD-1 blockade seems to worsen infection in some cases." (PMID 35432383, 2022). "Further work has then developed the story into showing clearly important roles for TBX21 in the regulation of interferon-γ production by regulating the accessibility of the IFNG gene through chromatin remodeling in the context of infection." (PMID 36230517, 2022). "We found up‐regulation of Notch ligands (NLs) and Notch receptors (NRs) on phagocytes and IFNγ+ CD4+ T cells upon infection in lungs and lymph nodes." (PMID 35603470, 2022). "As expected, we observed a significant increase in IFNγ production in response to S-peptides and infection status (99% increase, FDR < 0.1)." (PMID 35313592, 2022). "Memory T-cell interferon gamma release or proliferation assays in response to SARS-CoV-2 antigens provide an alternative means of assessing prior exposure to infection." (PMID 35732870, 2022). "The interferon-gamma release assay was originally validated to study T cell responses following natural infection, where it displays 98% sensitivity." (PMID 35420363, 2022). "CXCL10 and CXCL11 are chemokine ligands that recruit the leukocytes which drive the IFNγ-response, including Th1 polarisation, leukocyte activation and suppression of infection-induced genes in the urothelium (reviewed)." (PMID 35194151, 2022). "We carried out anti-HA immunoprecipitation in IFNγ-stimulated primary C57BL/6J murine embryonic fibroblasts (MEFs) infected with either PRU ROP1-HA or parental PRUΔKU80 at 24 hours post-infection." (PMID 36476844, 2022). "Coinfected animals treated with anti-mouse IFNγ displayed comparable ONNV tissue viral loads at 3, 6, 12, and 24 hpi than isotype-control treated mice, suggesting a major role of IFNγ in the antiviral effects exerted by preexisting Plasmodium infections." (PMID 35039441, 2022). "In the early stages of infection, macrophages bind to receptors on NK cells and secrete IL-12 leading to the production of IFNG." (PMID 36420258, 2022). "In this study, IL-27 was responsible for reducing the levels of TNF and IFNγ required for parasite control, therefore favoring infection." (PMID 35384718, 2022). "These TPT options of 4R (daily rifampicin for 4 months) and 3HP (once weekly rifapentine and isoniazid for 3 months) are now available in Brazil, as is the interferon-gamma release assay to test for infection." (PMID 35215139, 2022). "While a growing body of literature suggests that immune responses distinct from the canonical Th1 response can control infection, these CC strains are the first example of an animal model in which IFNγ appears to be dispensable." (PMID 35112666, 2022). "The phenotype of M1 macrophages is activated by infection and pro-inflammatory Th1 cytokines, including bacterial lipopolysaccharide (LPS), interferon-gamma (IFN-γ), and tumor necrosis factor-α (TNF-α)." (PMID 36429021, 2022). "This indicates that all mice immunologically responded to subsequent PICV infection with increasing splenocyte numbers, but showed minor increases in the overall IFNγ response, measured after α-CD3 stimulation." (PMID 36298848, 2022).
infection (continued). "Peripheral blood was collected at 6, 12 and 18 months post-vaccination, and infection status was determined using the IFNγ release assay in conjunction with the DIVA (Detecting Infected amongst Vaccinated Animals) antigens ESAT-6, CFP-10 and Rv3615c." (PMID 35565515, 2022). "It has been demonstrated that MIF plays a critical protective role during acute T. cruzi infection, by inducing the production of several pro-inflammatory cytokines, including IL-12, IL-18, TNF, IL-1β, and IFNγ, during the early phase of infection." (PMID 35464430, 2022). "Interferon-gamma (IFN-γ) is a remarkably small molecule that is used in clinical treatments as it participates in immune response and resistance against infections." (PMID 35812858, 2022). "Pathways related to genes modulated by TNFα/IFNγ involved pro-inflammatory signaling, infection, MAPK, and Ca2+ signaling." (PMID 35578269, 2022). "It was noted that mice inoculated with 140Gy irradiated parasites displayed a higher standard deviation when measuring Th1 type responses, mediated by IFNγ and TNFα which are essential when controlling the first peak of infection." (PMID 35634275, 2022). "Day of euthanasia also significantly influenced all targets except Cox1; relative to placentae from mice infected at E6.5 (i.e., E15.5), transcripts for Ifnγ, Tnf, Il1β, Il10, and Cox2 in placentae from E8.5 infections (i.e., E16.5) were all elevated." (PMID 35312688, 2022). "Mechanistically, the role of IFNγ in restricting ONNV infection was confirmed in in vitro infection assays through the generation of an IFNγ receptor 1 α chain (IFNγR1)–deficient cell line." (PMID 35039441, 2022). "The adaptive cytokines IFNγ and IL-2 as well as the IFNγ-induced chemokine IP-10 were the key correlates of prior exposure by infection and vaccination." (PMID 35812430, 2022). "As predicted, infection with the resulting strain ΔospC1/C3, pB led to minimal cell death, when compared with ΔospC1/C3 Shigella after IFNβ or IFNγ treatment." (PMID 35568036, 2022). "Although IFNγ expressing cells were maintained in Mtb-HT1 at 4 weeks of infection, there was nonetheless a marked contraction of IL-17+ T cells." (PMID 35173157, 2022). "It would seem that IL21 and IFNγ are important early in the infection, while a week after acute infection the cells take on a plasma cell precursor signature." (PMID 36380692, 2022). "We found total IFNγ concentrations in lung homogenate supernatants to be significantly higher in mice infected with 4334 than H37Rv at day 14 post infection." (PMID 35695454, 2022). "A second pathway is mediated by interferon-gamma (IFN-γ), which is produced by immune cells around 24–26 h after infection." (PMID 35408735, 2022). "Beyond promoting ISG transcription, IFNγ-mediated augmentation of innate immune responses, including antigen presentation, makes it a key link between innate and adaptive responses during infection." (PMID 35634328, 2022). "Knockdown of SUMO-1, UBA2, and UBC9 significantly upregulated the production of NO in infected and LPS- and IFNγ-stimulated macrophages by >2-fold at 24 h post-infection." (PMID 35734580, 2022). "Early in a blood-stage infection, a large number of IFNγ-secreting Th1 cells are produced, whereas Th2-like responses govern during the chronic phase of infection." (PMID 35039441, 2022). "Ongoing studies examining CD4+ T cell responses at the site of infection and the contribution of other cell types that produce IFNγ should further our mechanistic understanding of vaccine-mediated protection." (PMID 36248898, 2022). "Once activated, MAIT cells are robust secretors of IFNγ and cytotoxic mediators in acute infection scenarios." (PMID 35056597, 2022). "IFNγ can be produced by T helper 1 (Th1) cells and increases the cell-mediated response during an infection, but can be counteracted by IL-10 that has an anti-inflammatory and immune suppressive effect." (PMID 36641993, 2022).
infection (continued). "Infection leads to release of various pro-inflammatory cytokines, such as interleukin (IL)-1α, IL-6, tumor necrosis factor-alpha (TNFα), and interferon gamma (IFN-γ)." (PMID 35874547, 2022). "Negative hematological changes including increased inflammatory cytokines such as tumor necrosis factor-alpha (TNF-alpha), interferon-gamma (IFN-γ), and interleukin 6 (IL-6) are prominent in cases with severe infection." (PMID 35627841, 2022). "A statistically significant increase in the fraction IFNγ-producing of ERKSEM P14 CD8+ T cells compared to WT was seen on Day 10 post infection." (PMID 36846018, 2022). "C. burnetii-specific IFNγ and IP-10 responses in naturally exposed study participants more than a decade past infection were as high or higher than those observed 4-5 weeks after vaccination." (PMID 35812430, 2022). "It has also been shown that host immune response genes, including IL-4, CXCL10, IL-6, TNFα and IFNγ, are more active with NiV Malaysia infection compared to NiV Bangladesh." (PMID 35632678, 2022). "Conversely, other protozoan parasites highly prevalent in the tropics and known to induce the up-regulation of IFNγ in response to infection such as Leishmania spp." (PMID 35039441, 2022). "Supernatant of indole producing bacteria such as Prevotella intermedia and Prevotella nigrescens promotes CT infection in presence of IFNγ." (PMID 36560972, 2022). "At the protein level MCM2 was significantly induced by BKPyV-infection (p < 0.001) and that increase was significantly suppressed by IFNγ (p < 0.01)." (PMID 35194151, 2022). "IFNγ levels were 2.7-fold lower in septic shock patients compared with patients with infection (3.2 pg/mL [2.23–9.21] vs 8.58 pg/mL [3.84–27.01], p < 0.05)." (PMID 36536294, 2022). "In a multivariate model testing both status and day, membership in the E16.5 group was a significant predictor for Ifnγ, Tnf, Il1β, Il10, and Cox2 abundance (p ≤ 0.0306), while holding infection status constant." (PMID 35312688, 2022). "The proportion of IFNγ+ CD8+ T cells in the SP group was significantly higher than that in the RP group after infection." (PMID 35458449, 2022). "Early post-infection IFNγ expression in NK cells was enhanced equally in both diet groups, which was similar to our previous study with SE-infected chickens fed a standard diet." (PMID 35120583, 2022). "The immune cells in the lungs activate and produce large numbers of cytokines, mainly IFNγ and IFNα, to resist infection." (PMID 35458449, 2022). "To provide in vivo evidence that IL-22 links IL-18 to upregulate T-cell production of IFNγ in response to AIEC infection, we first investigated how the injection of recombinant IL-18 into Il-22−/− mice contributes to host defence." (PMID 35169117, 2022). "On infection and stimulation with IFNγ, the expression of BRG1 decreased significantly at 3 h (~ 86.6%, P = 0.016), 6 h (~ 94.4%, P = 0.012) and 24 h (~ 91%, P = 0.01) in comparison to the uninfected, stimulated cells." (PMID 35433496, 2022). "At 7 d.p.i., we observed comparable parasite numbers in the spleens of both infection routes, so we decided to assess splenic DC maturation as well as IFNγ production by CD4 and CD8 T cells via flow cytometry." (PMID 35898505, 2022). "Other infection- and IFNγ-treatment-dependent factors are likely involved in regulating its Tg control function." (PMID 34931666, 2022). "Among those, the highest fold changes in the infected liver were for Nos2 (log2FC > 10), Ifnγ (log2FC > 8), Tnf (log2FC > 5), and Il21 (log2FC > 6.6), denoting the sustained high inflammatory environment in this tissue during late infection." (PMID 35384718, 2022). "Although degranulation was unchanged, the fraction of IFNγ-producing CD8+ T cells was increased in ASP1570-treated mice at Day 35 post infection compared to vehicle-treated mice." (PMID 36846018, 2022).